ETS1 (ETS proto-oncogene 1, transcription factor)
Diseases named in the same sentence as ETS1 in open-access papers (continued):
Sharing a sentence is not in itself a finding about the gene and the disease.
melanoma (50 papers, 2005 to 2025). A malignant, usually aggressive tumor composed of atypical, neoplastic melanocytes. "Transfer of Ets1-deficient OT-I cells or pmel cells (recognizing the B16 melanoma antigen gp100) reduced B16-OVA and B16-F10 tumour growth, respectively." (PMID 37968405, 2023). "The ETS-1-miR-222 circuitry was also associated with melanoma progression, miR-222 induction being strictly dependent on the constitutive ETS-1 phosphorylation and compartmentalization in metastatic tumors and ETS1 directly targeted by miR-222." (PMID 32645881, 2020). "Accordingly, with respect to BRAFV600E-mutated melanoma, both phosphorylation of ETS1 and upregulation of GABPB via Fos have been shown to link oncogenic BRAF signaling to activation of the mutant TERT promoter." (PMID 31391125, 2019). "To further validate this finding we analyzed publicly available expression data of an ETS1 siRNA knockdown experiment in a melanoma cell line with TERT promoter mutation and found a downregulation of TERT compared to controls." (PMID 31888467, 2019). "The results were validated by using the well-known TERT regulation by the ETS1 transcription factor in a subset of melanomas with mutations in the TERT promoter." (PMID 31888467, 2019). "Accordingly, a recent study in melanoma has shown that the C228T variant, the predominant mutation detected in our panel, is more efficiently activated by ETS1 as compared to the other TERT promoter mutations." (PMID 31391125, 2019). "Our study provides evidence of a direct link between TERT expression and MAPK pathway activation through the ETS1 transcription factor in melanoma cells carrying a TERT promoter mutation." (PMID 27449293, 2016). "In fact, melanoma malignancy is associated more with the RAS/RAF/ERK constitutive activation of ETS-1 than with ETS-1 total quantity, which also includes variable amounts of unphosphorylated or serine-phosphorylated fractions." (PMID 21711453, 2011). "Moreover, the association between elevated Ets-1 expression and melanoma malignancy underscores it critical role in promoting melanoma cell migration, further suggesting its regulatory function in normal MCs and/or melanoblasts." (PMID 41310821, 2025). "Moreover, Ets-1 has been implicated in activating c-Met expression in melanoma and hepatocellular carcinoma cells, and its level correlates with poor prognosis." (PMID 39468027, 2024). "Beyond these melanoma-related models, Ets1-deficient OT-I cells improved therapeutic efficacy against OVA-expressing EL4 lymphoma (E.G7-OVA) and Lewis lung carcinoma (LLC-OVA) tumours, which was associated with enhanced intratumoral OT-I and Tex cell accumulation." (PMID 37968405, 2023). "That result suggested that ETS1 could be the transcription factor linking the activation of the MAPK pathway to the expression of TERT in melanoma cell lines harboring TERT promoter mutations." (PMID 27449293, 2016). "Ets-1 has also been linked to melanoma and lung tumor metastasis." (PMID 22971289, 2012). "For example, in melanoma cells, Ets-1 cooperates with PAX3 to increase the transcription of the c-Met gene." (PMID 39468027, 2024). "The ETS family function has been poorly studied in melanoma, with only ETS1 described as favoring invasion and being involved in resistance to MAPKinh." (PMID 35884430, 2022). "ETS1 can promote aggregation and invasion of melanoma, and ETV2 is required during tumor angiogenesis; meanwhile, the role of the rest of the ETS family members is largely unclear." (PMID 33424867, 2020). "In particular, the overexpression of nuclear ETS1 was related to drug resistance to vemurafenib in melanoma." (PMID 33203790, 2020).
melanoma (continued). "Expression of the Ets-1 mutant was diminished (1.9-fold) when compared with the WT protein in melanoma, but equivalent expression was achievable in HEK293T cells." (PMID 28198367, 2017). "Here the authors show that Usp9x regulates the stability of the transcription factor Ets-1 that in turn impacts metastatic melanoma through increased expression of NRAS." (PMID 28198367, 2017). "Within this hit list, we identified Ets-1 as a Usp9x substrate and key mediator of Usp9x dependence in melanoma." (PMID 28198367, 2017). "Overall, Usp9x appears to control ubiquitination of proteins essential in melanoma 3D growth (Ets-1) and attenuation of kinase signalling (Dusp4)." (PMID 28198367, 2017). "Usp9x and Ets-1 levels are coincidently elevated in melanoma with highest levels detected in metastatic tumours versus normal skin or benign skin lesions." (PMID 28198367, 2017). "To define a mechanism for regulation of NRAS expression by Usp9x in melanoma, we examined the effect of Usp9x (or Ets-1) on NRAS promoter activity." (PMID 28198367, 2017). "Expression of both WT and mutant Ets-1 increased colony number and 3D growth of melanoma; however, after normalizing for expression levels, the K388R mutation conferred greater tumorigenicity compared with overexpression of the WT protein." (PMID 28198367, 2017). "In the present study, we showed that ETS1 is expressed in melanoma cell lines and is constitutively phosphorylated by ERK on Thr38 in melanoma cell lines due to the activation of the MAPK pathway associated with BRAF or NRAS mutations." (PMID 27449293, 2016). "ETS1, expressed in melanoma cell lines, undergoes activating phosphorylation by ERK at Thr38 residue as a consequence of constitutively activated MAPK pathway." (PMID 27449293, 2016). "We investigated the role of ETS1 transcription factor, which has previously been involved in the development and invasion of melanoma." (PMID 27449293, 2016). "ETS1 is expressed in melanoblasts in normal adult melanocytes and in transformed cells; however, its role in melanoma progression is unclear." (PMID 27449293, 2016). "As SOX10, YY1, TFAP2A, and ETS1 all have important roles in melanocytes and/or melanoma, the MAREs identified here define a combinatorial signature of TFs critical for gene regulation in this lineage." (PMID 25803486, 2015). "In melanomas, ETS-1 has been recently identified as a key factor in upregulation of Mcl-1 gene, upon endoplasmic reticulum stress, and thus in the resistance of melanoma cells to apoptosis." (PMID 24086527, 2013). "Previous study has shown that ETS (ETS1) transcription factor mediates adaptation to ER stress in melanoma cells, supporting the potential role of ERG in the regulation of ER function related genes in prostate cancer." (PMID 22761906, 2012). "Differently from 293FT cells or early stage melanomas, where unphosphorylated ETS-1 represses miR-222 transcription, in metastatic melanoma the constitutively Thr-38 phosphorylated fraction of ETS-1 induces miR-222." (PMID 21711453, 2011). "As shown melanocytes and primary melanomas, expressing high levels of total ETS-1, displayed a barely or undetectable phosphorylated fraction, whereas most of the ETS-1 protein was activated through T38-phosphorylation in metastatic melanomas." (PMID 21711453, 2011). "Despite its stepwise decreased expression along with melanoma progression, the oncogenic activity of ETS-1 relies on its RAS/RAF/ERK-dependent phosphorylation status more than on its total amount." (PMID 21711453, 2011). "ETS-1 is expressed in melanocytes migrating from the neural crest during embryogenesis and in normal adult melanocytes, but its role in malignant melanomas appears controversial." (PMID 21711453, 2011). "In Me1007 primary melanoma cell line, the low level of nuclear P-T38 ETS-1 (red) made it difficult to detect when merged with the strongly stained total ETS-1 (green) (left)." (PMID 21711453, 2011).
melanoma (continued). "To assess the functional role of ETS-1 in miR-222 regulation and disease progression, we tested the tumorigenic properties of melanoma cells forced either to overexpress or repress ETS-1." (PMID 21711453, 2011). "Traditional and qRT-PCR as well as Western blot analyses on nuclear extracts showed that all these melanoma cell lines expressed ETS-1 at levels inversely related to melanoma malignancy." (PMID 21711453, 2011). "ETS-1 downregulation was confirmed at both mRNA and protein levels in miR-222-transduced Me1007 and Me1402/R primary melanoma cell lines." (PMID 21711453, 2011). "Our results, showing miR-222-induced downregulation of ETS-1 during melanoma progression, at first sight speak against a possible tumorigenic role of ETS-1." (PMID 21711453, 2011). "Torlakovic and collaborators (2004) analyzed a large collection of nevi, primary and metastatic melanomas from their archives for ETS-1 expression." (PMID 21711453, 2011). "The reverse effect on ETS-1 regulation was confirmed in Me665/1 and A375M metastatic melanomas by miR222-specific antagomir transfection." (PMID 21711453, 2011). "To confirm an ETS-1-specific contribution unambiguously, we silenced it in A375M melanoma cells using DsiRNA, obtaining a 75% downregulation of ETS-1 as evaluated by qRT-PCR (left) and Western blot." (PMID 21711453, 2011). "Here, we reveal the existence of a novel ETS-1↔miR-222 circuitry in which both miR-222 and the phosphorylated activating portion of ETS-1 are relevant to melanoma progression." (PMID 21711453, 2011). "According to these results, qRealtime PCR showed that miR-222 upregulation was a consequence of either ETS-1 silencing in primary melanomas or ETS-1-enforced expression in metastatic melanomas." (PMID 21711453, 2011). "A similar ETS-1-dependent repressive function was observed when early stage Me1007 melanoma, expressing high levels of barely or unphosphorylated ETS-1, was used as a recipient for the promoter luciferase assays." (PMID 21711453, 2011). "WB analysis showed a significant inverse correlation between total ETS-1 and its T38-phosphorylated fraction during melanoma progression." (PMID 21711453, 2011). "For example, the role of Protein Kinase Cα (PKCα) should be explored because it is implicated in cell proliferation, cell migration, and tumor cell invasion in melanoma and increases the stability of the ETS-1 protein." (PMID 18958307, 2008). "Interestingly, recent studies demonstrated activity of YK-4-279 against critical ETS1/PAX3 interactions in melanoma." (PMID 39448867, 2025). "Therefore, we pursued a mechanism of TNF expression in melanoma based on Sp1, Ets-1, and cJUN activity." (PMID 37043573, 2023). "Finally, PAX3 (paired box gene 3 transcription factor) was shown, in conjunction with the transcription factor ETS1, to promote melanoma cells proliferation and metastasis by increasing the expression of MET, the HGF receptor." (PMID 35052351, 2021). "We previously noted that Ets-1 TF expression was induced by BRAFi and MEKi in melanoma." (PMID 33613844, 2021). "To validate that ETS1 is a key regulator in the samples with TERT promoter mutation, we investigated published microarray data from experiments in which ETS1 was knocked down in melanoma cells with TERT promoter mutation." (PMID 31888467, 2019).
melanoma (continued). "From the ETS family of TFs, ISMARA predicted GABPA, ELF2 and ELF5 with very low significance, while MIPRIP identified ETS1 as a highly significant regulator of TERT in the melanoma samples with a TERT promoter mutation." (PMID 31888467, 2019). "Besides ETS1, we predicted AR, E2F1 and JUND as the most significant regulators in melanoma patients with a TERT promoter mutation." (PMID 31888467, 2019). "Through Usp9x-mediated, site-specific deubiquitination, Ets-1 proteasomal destruction is inhibited, resulting in Ets-1 accumulation and increased melanoma tumorigenicity, which could be blocked by inhibition of Usp9x activity or knockdown of Ets-1." (PMID 28198367, 2017). "ETS1 has been implicated as a predominant factor activating mutant TERT promoters in melanoma, but previous studies have reached differing conclusions on ETS1 expression relative to melanoma progression." (PMID 29262649, 2017). "Combined kinase and DUB inhibition was effective in completely suppressing NRAS-mutant melanoma in vivo, suggesting combination therapy may prevent resistance mediated by Ets-1 induction." (PMID 28198367, 2017). "Similar effects were noted in both NRAS and BRAF mutant melanoma cells following Ets-1 or Usp9x KD." (PMID 28198367, 2017). "ETS1 is reported to be important for TERT upregulation in melanoma." (PMID 29262649, 2017). "Our studies indicate that Usp9x may be a good therapeutic target in melanoma because of its effects on tumour expansion, regulation of Ets-1 stability, NRAS expression and response to kinase inhibitors." (PMID 28198367, 2017). "We further demonstrated that Ets-1 promotes NRAS gene expression, which may at least partly underlie the high sensitivity of melanoma to Usp9x inhibition and Ets-1 depletion." (PMID 28198367, 2017). "ETS1 also regulates genes involved in melanoma cell invasiveness: MMP1, MMP3 and integrin-β3." (PMID 26885752, 2016). "We assessed ETS1 protein and mRNA expression in melanoma cells after SOX9 silencing." (PMID 26885752, 2016). "ETS1 regulates key factors that promote melanoma development and survival." (PMID 26885752, 2016). "Indeed, in melanoma ETS-1 has a definitely more complex role than the apparent tumor-suppressive one, simply based on its downregulated expression in advanced tumors." (PMID 21711453, 2011). "In addition, a spatial redistribution of ETS-1 protein from the nucleus to the cytoplasm is also evidenced in advanced melanoma cells." (PMID 21711453, 2011). "Finally, it is important to mention the intriguing results obtained by transducing the dominant negative TM ETS-1 in the A375M and Me665/1 melanomas in that it induces a more aggressive behavior with respect to control cells both in vitro and in vivo." (PMID 21711453, 2011). "Indeed, ETS-1 loses its normal repressive function in melanoma, becoming a positive regulator of miR-222." (PMID 21711453, 2011). "Finally, based on our previous results showing the tumor-suppressor role of the promyelocytic leukemia zinc finger (PLZF) product in melanoma, we examined the possibility of an ETS-1/PLZF coordinated function." (PMID 21711453, 2011). "In addition, ETS1 has been identified to be deubiquitinated by Usp9x in melanoma." (PMID 40369168, 2025). "Given that ETS family members are also expressed in immune cells, such as ETS1 in T cells and ELK1 in B cells, we utilized scRNA-seq data to analyze the expression of the PEA3 subfamily, which was found to be associated with immune infiltration, in melanoma cells." (PMID 41502516, 2025). "Thus, we provide evidence that Usp9x plays an important role in Ets-1 regulation and melanoma tumorigenicity, in part through NRAS transcription which may be of particular importance in tumours driven by NRAS mutation." (PMID 28198367, 2017). "Furthermore, ETS1 was constitutively phosphorylated at threonine 38 in all melanoma cell lines." (PMID 27449293, 2016). "However, the role of ETS-1 in melanoma is far from being clearly demonstrated." (PMID 21711453, 2011).
melanoma (continued). "Finally, bearing in mind that our previous data showed that the absence of PLZF underlies melanoma progression by unblocking miR-221/-222 transcription, we evaluated the possibility of an ETS-1/PLZF integrated function." (PMID 21711453, 2011). "Considering the possible functional relevance of ETS-1 cellular topographic distribution, equal amounts of cytoplasmic and nuclear extracts obtained from Me1007 and A375M, as representatives of primary and advanced melanoma cell lines, were analyzed by immunoblot." (PMID 21711453, 2011). "Loss of ETS-1 expression was significantly associated with increased tumour cell proliferation by Ki-67 expression, and this is consistent with a proposed role in cell cycle regulation, although probably not through the p16 pathway in melanomas." (PMID 16189525, 2005). "COP1, which inhibits ultraviolet-B stimulated growth in plants, suppresses nuclear ETS1 and ETS1-mediated expression of BCL2 in the murine melanomas and in human melanoma cells." (PMID 40562100, 2025). "The top 5 cancers containing ETS1 alteration were BLCA, OV, mature B-cell lymphoma (MBL), melanoma, and ESCA." (PMID 36760475, 2023). "In contrast, other long-term MEKi acquired resistance cells were highly dependent solely on ABL1/2, which stabilized MYC and ETS1 proteins in an ERK-independent manner, and induced β-catenin nuclear localization to drive melanoma survival." (PMID 36765910, 2023). "Ets-1 is a known downstream target of the MAPK pathway, and cJUN is known to be dysregulated in melanoma." (PMID 37043573, 2023). "All MAPK inhibitors enhance LC residency because the MAPK pathway is required for Ets-1 activity and, consequently, for TNF expression in melanoma in the model." (PMID 37043573, 2023). "NRAS mutant melanoma cell growth and survival relies on continual NRAS expression, implying that USP9X-mediated stabilisation of ETS-1 drives tumorigenesis." (PMID 34066106, 2021). "USP9X was shown to interact directly with ETS-1 and prevent its proteasomal degradation through deubiquitination, promoting ETS-1 transcriptional activity at the NRAS promoter in melanoma cells." (PMID 34066106, 2021). "In particular, ELK3, ETS1, ETV1, ETV4, ETV5, and SPI1 were significantly upregulated in melanoma, whereas EHF, ELF3, ELF5, ERG, ETS2, ETV7, and SPDEF were significantly downregulated in the tumor." (PMID 33424867, 2020). "The mRNA levels of many transcriptional regulators that affect the level of pigmentation, including Sox10, Ets1, and Irf4, were also reduced while the expression of Tfap2 was strongly increased in both Melb-a melanoblasts and SK-MEL-147 melanoma cells." (PMID 32151278, 2020). "In two melanoma cell lines (SK-Mel29, WM1366), Usp9x activated NRAS promoter activity by ∼2-fold, while Ets-1 expression increased promoter activity by >2.5-fold." (PMID 28198367, 2017). "Both Usp9x and Ets-1 KD consistently and effectively suspended 3D growth of NRAS mutant melanoma derived from metastatic lesions." (PMID 28198367, 2017). "Our data show expression of ETS1 and its phosphorylation in an ERK-dependent manner in all melanoma cell lines included in the study." (PMID 27449293, 2016). "However, ETS1 inhibition induced only a partial reduction of TERT expression suggesting that other transcription factors may be involved in TERT expression in melanoma cells." (PMID 27449293, 2016). "To verify direct binding of ETS-1 to BS1 and BS2 on miR-221/-222 promoter, we carried out chromatin immunoprecipitation (ChIP) assays in Me1007 and A375M melanomas." (PMID 21711453, 2011). "We evaluated ETS-1 expression in a panel of melanoma cell lines at different stages of progression, including primary vertical growth phase (VGP) melanomas, as well as subcutaneous and lymph-node metastases." (PMID 21711453, 2011).